TERT (telomerase reverse transcriptase)
Diseases named in the same sentence as TERT in open-access papers (continued):
Sharing a sentence is not in itself a finding about the gene and the disease.
glioblastoma (continued). "Telomere maintenance mechanisms are crucial during DNA replication in glioblastomas, with TERT promoter mutations being the most prevalent alterations, indicating their key role in oncogenesis and integration into current GBM diagnostic procedures." (PMID 39767571, 2024). "Thus, the presence of any of the following five criteria is sufficient to designate an IDH-wildtype diffuse astrocytic glioma as glioblastoma: microvascular proliferation, necrosis, TERT promotor mutation, EGFR gene amplification, or 17/–10 chromosome copy number changes." (PMID 38553638, 2024). "Moreover, multifocal glioblastomas have a strong association with TERT promoter mutations in general, and one study suggests that 50% of these tumours are associated with c-Met overexpression based on immunohistochemistry, which is negatively correlated with survival and treatment response." (PMID 37239289, 2023). "Thus, up to now our retrospective data argue against standardized analysis for TERT promotor mutation status for the purpose of prognostic or therapeutic relevance in newly diagnosed IDH-wildtype glioblastoma that otherwise meets the histopathological and molecular diagnosis criteria." (PMID 36325373, 2022). "It has been reported that converting TERT -124 T to C using CjABE causes glioblastoma (GBM) cell senescence and inhibits GBM growth in vitro and in vivo, and knockout of the TERT coding region can inhibit cancer cell proliferation." (PMID 35053139, 2022). "Mutation of TERT promoter as a genetic event is frequently detected in 60–75% of glioblastomas (GBM), and associated with a poor prognosis." (PMID 32957941, 2020). "TERT-mutated glioblastoma (GBM) patients with MGMT methylation benefited from temozolomide (TMZ) treatment (HR = 0.33; 95% CI = 0.23–0.47; p-value < 0.001)." (PMID 32957941, 2020). "Cancers that are frequently associated with TERT promoter mutations include glioblastoma multiforme (GBM), melanoma, hepatocellular carcinoma, urothelial cancers, anaplastic thyroid cancer, and a variety of non-melanoma skin cancers." (PMID 32630460, 2020). "Two TERT promoter mutations (1 295 228 C>T and 1 295 250 C>T, referred to as124C>T and146C>T, respectively, in the following text), particularly the 124C>T mutation, have been identified in bladder cancer and glioblastoma, suggesting a role for TERT promoter mutations inhuman tumorigenesis." (PMID 27064992, 2016). "We found that mutations in the TERT promoter occurred in 74.2% of glioblastomas (GBM), but occurred in a minority of Grade II-III astrocytomas (18.2%)." (PMID 24722048, 2014). "Glioblastomas, predominantly IDH-wild-type, exhibit aggressive molecular features including TERT promoter mutations, EGFR amplification, PTEN loss, and chromosome 7/10 alterations, leading to rapid growth and poor outcomes." (PMID 41596318, 2026). "Beyond MGMT and TERT alterations, chromosomal aberrations are hallmark features of IDH-wildtype glioblastoma, particularly chromosome 7 gain (+7) and chromosome 10 loss (−10), which contribute to genomic instability and tumor aggressiveness." (PMID 41346390, 2025). "Telomerase reverse transcriptase (TERT) promoter mutations—found in up to 80% of IDH-wildtype and 28% of IDH-mutant glioblastomas—enable telomere maintenance and support cellular immortality." (PMID 40723205, 2025). "Glioblastoma, IDH wildtype are diffuse and astrocytic gliomas in adults with microvascular proliferation or necrosis or TERT promoter mutation or EGFR gene amplification or +7/−10 chromosome copy number chnges." (PMID 40949165, 2025).
glioblastoma (continued). "Isocitrate dehydrogenase (IDH)-wildtype adult-type diffuse astrocytic tumors with EGFR amplification, TERT promoter (TERTp) mutations, or combined gain of chromosome 7 and loss of chromosome 10 can be classified as glioblastomas (GBM), even with low histological grades." (PMID 40786409, 2025). "TERT mutations present in the vast majority of oligodendroglioma and IDH wildtype glioblastoma are mutually exclusive with ATRX mutations and alternative lengthening of telomerase seen in astrocytoma." (PMID 40949165, 2025). "Pathology results were consistent with recurrent glioblastoma (MGMT promoter methylated, TERT mutation positive)." (PMID 40778355, 2025). "Given the prognostic implications of TERT mutation when associated with wild-type IDH, the mutation has also been included in the WHO 2021 integrated diagnosis for glioblastoma." (PMID 39796751, 2025). "TERT can be activated through multiple mechanisms in several cancer types including primary glioblastoma, bladder, and hepatocellular cancers." (PMID 39974235, 2025). "In addition, certain TERT polymorphisms are associated with an increased risk of developing GBM, and an association between somatic TERT promoter mutations also results in a reduced OS of patients with primary glioblastoma." (PMID 38240992, 2024). "Glioblastoma, IDH-wildtype is molecularly characterized by TERT promoter (TERTp) mutation, EGFR amplification, or chromosome 7 gain and 10 loss (7 +/10−), in addition to characteristic pathological findings such as necrosis and microvascular proliferation." (PMID 38605367, 2024). "Gene alterations in TERT have also shown relative clonal stability between newly diagnosed glioblastoma and recurrent glioblastoma." (PMID 38928445, 2024). "BIBR1532, a telomerase inhibitor, showed a dose-dependent cytotoxic effect in cultured human glioblastoma cells after treatment, with reduced expression of TERT protein." (PMID 39518074, 2024). "In IDH1 wild-type glioblastomas with MGMT promoter methylation, individuals with conditions conducive to TERT promoter mutations exhibit better survival following standard radiotherapy and chemotherapy." (PMID 39131044, 2024). "In the whole series, 36 (90%) tumors were TERT-mutant (including 32 glioblastomas IDH wild type and 4 oligodendrogliomas) and the MGMT promotor was methylated in 33 (75%) cases." (PMID 39456559, 2024). "They found that TERT promoter-mutant glioblastoma cells are dependent on telomerase and showed typical features of telomere crisis when telomerase is lost." (PMID 39201386, 2024). "This was confirmed in the porcine glioblastoma model, where the diagnostic sensitivity for EGFRvIII improved by FUS-BBBO from 29% to 100%, and for TERT C228T from 43% to 71%." (PMID 38672658, 2024). "In a previous cohort however, the unfavorable prognosis of glioblastoma patients with TERT activation had been attributed to the older age of the patients and not to the subsequent telomerase activation per se." (PMID 38240992, 2024). "In this setting, the classifications include three genetic variables (TERT promoter mutation, EGFR gene amplification, +7/−10 chromosome copy number variations) as criteria to diagnose glioblastoma (grade 4), IDH-wildtype." (PMID 38674436, 2024). "In particular, the GABPA/B tetramer selectively binds and activates the mutant TERT promoter, thus inducing overexpression of the TERT gene in several tumour types, including glioblastoma, melanoma, hepatocellular carcinoma and bladder cancer." (PMID 38033865, 2023). "Genetic alterations common in glioblastoma, IDH-wildtype, were seen in two cases with available NGS data, including EGFR gene amplification, TERT promoter mutation, PTEN mutation, trisomy of chromosome 7, and monosomy of chromosome 10." (PMID 37686092, 2023).
glioblastoma (continued). "High TERT expression was first identified in vascular endothelial cells isolated from astrocytic tumours which correlated with the severity, such that glioblastoma samples expressed significantly higher TERT compared to low‐grade astrocytomas." (PMID 37041671, 2023). "Markers like Epidermal Growth Factor Receptor (EGFR) amplifications, Telomerase Reverse Transcriptase (TERT) promoter mutations, combined whole chromosome 7 gain, and combined whole chromosome 10 loss are crucial for diagnosing glioblastoma IDH wildtype." (PMID 37894355, 2023). "Two genes, AC017104.4 and UNC93B7, were found to be specific for patients with IDH1-wt, TERT-promoter-mutated, and MGMT-methylated glioblastoma." (PMID 37568598, 2023). "Chromosomes + 7/−10 was observed in 11 cases including the 8 cases with pathological features of glioblastoma and 3 LGG cases and was always associated with TERT promoter mutation." (PMID 36647073, 2023). "Both TERT C228T and C250T promoter mutants were associated with IDH wildtype, preserved 1p/19q, histone wildtypes, and ATRX retention in glioblastoma cases." (PMID 37665980, 2023). "Collectively, these recent reports highlight the need for early noninvasive imaging biomarkers of response to TERT silencing in order to achieve better precision medicine for glioblastoma patients." (PMID 36997627, 2023). "Retained ATRX is confirmed to be associated with IDH wildtype in glioblastoma, as well as with the presence of IDH-mutants, TERT mutants and 1p/19q codeletions, in oligodendroglioma." (PMID 37665980, 2023). "They lacked EGFR amplification, lacked combined trisomy of chromosome 7 plus monosomy of chromosome 10, and only rarely had TERT promoter mutation or CDKN2A homozygous deletion, which are hallmarks of conventional IDH-wildtype glioblastoma." (PMID 38079020, 2023). "Thanks to its ubiquitous distribution and elevated incidence, TERT appears as the perfect potential target in glioblastomas." (PMID 38201248, 2023). "The molecular landscape of multifocal glioblastomas is similar to their solitary counterparts; however, EGFR mutations, and concomitant EGFR, PTEN, and TERT promoter mutations occur at an increased incidence." (PMID 37239289, 2023). "For example, the guidelines suggest using mutations in IDH, the TERT promotor, and epidermal growth factor receptor (EGFR) as markers for glioblastoma (GBM)." (PMID 37241023, 2023). "EGFRvIII-positive brain tumors were all glioblastoma IDH-wildtype, most with concurrent TERT promoter mutation (14 of 16), EGFR amplification (13 of 16), and EGFR mutation (8 of 16)." (PMID 38201434, 2023). "Combined analysis of TERT mutations within the context of the status of other genes, including EGFR and IDH, can further refine the prognostic classification of glioblastoma." (PMID 37759708, 2023). "This review aims to provide an update of the evidence on the biology and physiopathology of TERT, exploring promising novel strategies and limitations to TERT inhibition in patients with glioblastomas." (PMID 38201248, 2023). "Recently, we found that sonobiopsy improved the detection sensitivity of glioblastoma (GBM) tumor-specific EGFRvIII mutation from 7.14 to 64.71% and TERT C228T from 14.29 to 45.83% in a mouse GBM model." (PMID 37717084, 2023).
glioblastoma (continued). "The remaining tumours which lack IDH mutations are termed IDH wildtype glioblastoma (GBM) and are most often associated with TERT promoter mutations, gains of chromosome 7/EGFR, and loss of chromosome 10, characteristic of high grade (grade 4) GBM." (PMID 35526077, 2022). "Bell and colleagues sequentially knocked-down thirteen ETS transcription factors in two glioblastoma lines and showed that GABPA selectively reduces TERT transcription in the presence of the c.-124C > T mutation." (PMID 35053525, 2022). "Overall, GABPA seems a solid candidate to explore TPM-specific epigenetic blockade of TERT re-expression in glioblastoma, but its role in thyroid cancers remains uncertain." (PMID 35053525, 2022). "TERT promoter (TERTp) mutations are the most common non-coding mutations in cancer, including the majority of IDH1 wild-type (IDH1-WT) primary glioblastoma (GBM)." (PMID 36130485, 2022). "For IDHwt glioblastomas, 2021 WHO Classification identifies that TERT promoter mutations and EGFR alterations are characteristically found." (PMID 36380219, 2022). "Reduction of GABPβ1L in orthotopic xenotransplanted mice with TERT promoter mutant glioblastoma cells reduced the tumor burden and prolonged the overall survival time of mice." (PMID 35903534, 2022). "Our findings are consistent with the concept that IDH-WT/ TERT-mutant diffuse gliomas represent a clinicopathological part of primary glioblastomas and their precursors." (PMID 34558656, 2022). "TERT expression is limited to stem cells and cancer cells, therefore, to selectively measure TERT expression in tumor cells from this TERTp duplicated glioblastoma, we performed TERT RNA in situ hybridization (RNAscope) on FFPE slides." (PMID 36114166, 2022). "Whole-exome sequencing and pathological examination revealed glioblastoma, IDH1 wild type, PTEN deficient, TERT mutated, NF1mutated, MGMT unmethylated." (PMID 36271359, 2022). "They subsequently showed that GABPA is also able to upregulate mutant TERT in glioblastoma and melanoma cells, but it does so, at least partially, via long-range chromatin interactions." (PMID 35053525, 2022). "A phase I/II trial on seven glioblastoma patients receiving a TERT activity-targeted vaccine showed that all recipients had statistically significant longer progression free survival compared to historical-matched controls (694 days vs 236 days)." (PMID 35436952, 2022). "These genes were involved in pathways directly related to glioblastoma, invasiveness signature, TERT-related, and general cancer pathways." (PMID 35521558, 2022). "Several studies, typically using siRNA silencing, reporter assays, and ChIP approaches, on glioblastoma cells carrying TPMs demonstrated that the ETS factor GABPA controls TERT mutant promoter expression." (PMID 35053525, 2022). "Based on WHO 2021 classification and other previous reports has already established that Chr7 gain & Chr10 loss, TERT mutation along with EGFR expression and MGMT promoter methylation are the strongest predictor of survival in glioblastomas." (PMID 35144680, 2022). "In glioblastoma cells harboring the TERT promoter mutation, GABPB1 depletion led to reduced TERT expression coupled with diminished telomerase activity followed by progressive telomere attrition and eventual loss of oncogenic potential." (PMID 35549739, 2022). "Advanced MRI, including arterial spin labeling imaging (ASL), DWI, and dynamic susceptibility contrast perfusion imaging (DSC), is used to assess MGMT and TERT status in patients with glioblastomas." (PMID 36471242, 2022). "In glioblastomas and thyroid carcinomas, the GABPA-GABPB1 complex was shown to activate the mutated TERT promoter." (PMID 36713366, 2022).
glioblastoma (continued). "In contrast, continued GABPA knockdown in U251 glioblastoma cells confirmed the previously shown significant reduction in TERT expression." (PMID 35053525, 2022). "Patients with IDH1/2-wildtype glioblastomas harboring CDKN2B, EGFR, and TERT promoter mutations who underwent GTR were associated with improved OS when compared to other EOR in the FDR-adjusted analysis." (PMID 35156038, 2022). "The cIMPACT-NOW update 6 first introduced glioblastoma diagnosis based on the combination of IDH-wildtype (IDHwt) status and TERT promotor mutation (pTERTmut)." (PMID 34902093, 2022). "To better evaluate the effects of TERT on radiation and survival, we analyzed TERTmut and TERTwt IDHwt glioblastoma subgroups." (PMID 36380219, 2022). "The presence of one or more of the following three genetic parameters EGFR gene amplification, TERT promoter mutation and 7+/10–, is required to upgrade astrocytoma, IDH-wildtype to glioblastoma, IDH-wildtype." (PMID 36425564, 2022). "Specifically, IDH-WT glioblastoma usually contains higher level of epidermal growth factor receptor (EGFR) amplification, TERT promoter mutation and PTEN deletion, etc.." (PMID 35135556, 2022). "For example, the Oncomine v2 panel lacks evaluation of the TERT promoter, which is diagnostically critical for glioblastoma and CNS WHO grade 3 meningiomas, and it is recurrently altered other tumors, including oligodendroglioma." (PMID 36397144, 2022). "The duplications recruit a GABP tetramer by virtue of the native ETS motif and its precisely spaced duplicated counterpart, activate the promoter and are clonal in a TERT expressing multifocal glioblastoma." (PMID 36114166, 2022). "Glioblastoma must have wild-type IDH gene and some characteristics, such as TERT promoter mutation, EGFR gene amplification, microvascular proliferation, among others." (PMID 35804976, 2022). "For example, miR-21 represses TERT through a STAT3 transcription in glioblastoma cells and regulates TERT via the PTEN/ERK1/2 signaling pathway in colorectal cancer." (PMID 33802026, 2021). "Our results showed that the expression levels of TERT mRNA were higher in glioblastoma samples than that in healthy controls." (PMID 33763172, 2021). "Consistent with above, telomerase activity and TERT expression were downregulated in brain cancer cells A-172 (glioblastoma) and ONS-76 (medulloblastoma) after exposure to HDAC inhibitors." (PMID 33802026, 2021). "In recent series, it appears that the TERT promoter gene mutation is associated with poor outcomes in IDH wild type glioblastoma and favourable outcomes in IDH mutated glioblastoma." (PMID 34683160, 2021). "In general, TERT overexpression was the main mechanism of telomere elongation in IDH wild-type glioblastoma, except for the PDGFRA subgroup." (PMID 34572759, 2021). "By screening our GBM genomic data, ODs and IDHWT glioblastomas nearly exhibit a robust expression of TERT." (PMID 34884508, 2021). "In this study, we presented that TERT mRNA expression levels are the highest in the primary glioblastomas compared to normal brain tissue." (PMID 34194624, 2021). "In our cohort, TERT promoter mutations and a chromosome 7/10 signature in at least half of the samples are shared findings with conventional IDH-wildtype glioblastoma and further imply the belonging to this entity." (PMID 33876327, 2021). "TERT promoter mutations (TPMs) that increase TERT expression are found in several cancers, including HCC, melanoma, basal and squamous cell carcinoma, glioblastoma, and bladder and thyroid cancer." (PMID 34771685, 2021). "This review also addresses the importance of interplay between CD133, Wnt/β-catenin and TERT signaling pathways in GSCs and outlines the future therapeutic goals for glioblastoma treatment." (PMID 33869033, 2021).